RPS6 (ribosomal protein S6)
Diseases named in the same sentence as RPS6 in open-access papers (continued):
Sharing a sentence is not in itself a finding about the gene and the disease.
endometrial cancer (1 paper, 2020). Primary or metastatic malignant neoplasm involving the endometrium (mucous membrane that lines the endometrial cavity). "The analysis indicated phosphorylation of ribosomal protein S6, which is mediated by an mTORC1 target p70S6K, to be significantly more elevated in endometrial cancer tissues than that in normal tissues." (PMID 32899752, 2020).
enterovirus infections (1 paper, 2025). "However, it is intriguing that p70S6K and rpS6 have been reported to cooperate with increased cap-dependent translation, a target usually compromised upon enterovirus infections, to compete with host mRNAs for translation factors and ribosomes." (PMID 40869312, 2025).
epilepsy (1 paper, 2025). A brain disorder characterized by episodes of abnormally increased neuronal discharge resulting in transient episodes of sensory or motor neurological dysfunction, or psychic dysfunction. "We found that genes of the mTOR pathway (RPS6, RHEB, EIF4E) were highly expressed in the PY2 pyramidal neurons, consistent with the activation of the mTOR pathway in histopathological neurons in the epileptic focus of drug-resistant epilepsy." (PMID 40026248, 2025). "In addition, the mTOR pathway genes RPS6, TPI1, ENO1, and PGK1 are enriched in PY2-like cortical neurons of brain samples from patients with epilepsy compared with people in a nonepilepsy control group." (PMID 40026248, 2025).
Ewing family tumor (1 paper, 2015). "Knockdown of RPS6 by siRNA reduced the survival of Ewing family tumor cell lines with near complete cell death in a siRNA library screening." (PMID 25955731, 2015).
Ewing sarcoma (1 paper, 2021). A small round cell tumor that lacks morphologic, immunohistochemical, and electron microscopic evidence of neuroectodermal differentiation. "RPS6-KD by siRNA reduced the survival of Ewing sarcoma cell lines over time." (PMID 35008473, 2021).
Glucose intolerance (1 paper, 2011). Glucose intolerance (GI) can be defined as dysglycemia that comprises both prediabetes and diabetes. "These mutations resulted in reduced overall size, glucose intolerance, and muscle weakness, as well as reduced cell size, however, overall protein translation was not grossly reduced in rpS6 knock-in cells." (PMID 22195043, 2011).
hepatopathies (1 paper, 2023).
Impaired glucose tolerance (1 paper, 2016). An abnormal resistance to glucose, i.e., a reduction in the ability to maintain glucose levels in the blood stream within normal limits following oral or intravenous administration of glucose. "rpS6 phosphorylation deficient mice exhibit decreased β-cell size and impaired glucose tolerance." (PMID 26919188, 2016).
injury (1 paper, 2025). Damage inflicted on the body as the direct or indirect result of an external force, with or without disruption of structural continuity. "Alterations in the phosphorylation level of rpS6 were also observed in response to traumatic brain injury in rats as early as 30 min to 24 h after injury." (PMID 40758329, 2025).
keloid (1 paper, 2016). An irregularly shaped, elevated mark on the skin caused by deposits of excessive amounts of collagen during wound healing. "Phosphorylation of the ribosomal protein S6, a marker of mTOR (a mammalian target of rapamycin) pathway activation, is strongly increased in hypertrophic scars and keloids; RAPA is the inhibitor of mTOR, which could downregulate the expression of collagen and fibronectin." (PMID 27094512, 2016).
leiomyosarcoma (1 paper, 2024). An uncommon, aggressive malignant smooth muscle neoplasm, usually occurring in post-menopausal women. "In our experimental conditions, we observed a similar effect; trabectedin treatment increases the phosphorylation of the ribosomal protein S6, an effect that is avoided by treating leiomyosarcoma cells with mTOR inhibitor rapamycin." (PMID 38758230, 2024).
lipoma (1 paper, 2021). A benign, usually painless, well-circumscribed lipomatous tumor composed of adipose tissue. "A PTEN downregulation in adipocyte progenitor cells of approximately 50% as observed in lipoma cells of a patient with PHTS leads to a several-fold activation of the PI3K downstream targets AKT and ribosomal protein S6." (PMID 34273354, 2021).
liver fibrosis (1 paper, 2024). "Consistently, we noted specific upregulation of genes enriched in ALK signaling in aged Myof (CLTC, RPS6, STAT3, etc.), which is studied extensively in liver fibrosis." (PMID 37378670, 2024).
male infertility (1 paper, 2021). The inability of the male to effect fertilization of an ovum after a specified period of unprotected intercourse. "Their data are consistent with our observation for hyperphosphorylation of rpS6 and male infertility." (PMID 33633267, 2021).
malignant glioma (1 paper, 2021). A grade III or grade IV glioma arising from the central nervous system. "In addition, our previous results also revealed that, of these ribosomal proteins, RPS6 expression was upregulated in high malignant glioma patients." (PMID 34831193, 2021).
metastasis (1 paper, 2016). The spread or migration of cancer cells from one part of the body (where they first appeared) to another. "Multivariate Cox regression analysis included rpS6 expression, Karnofsky performance status, tumor extent, regional lymph node metastasis, distant metastasis, grade of malignancy, type of surgery, gender, and histological subtype." (PMID 26506236, 2016).
Miscarriage (1 paper, 2024). A pregnancy that ends at a stage in which the fetus is incapable of surviving on its own, defined as the spontaneous loss of a fetus before the 22th week of pregnancy. "These were stated to correlate with miscarriage rate in previous studies.RPS6, is a substrate for inducible phosphorylation, downstream effector of mTOR pathway." (PMID 38777848, 2024).
myocarditis (1 paper, 2011). Myocarditis is a condition that is characterized by inflammation of the heart muscle (myocardium). "Finally, we tested whether EAM rats had significantly increased levels of activated rpS6 because human patients with post-myocarditis show nuclear hypertrophy with an increased translation efficiency, and recent studies have shown that activation of rpS6 enhances translation and cell growth in vivo." (PMID 22014063, 2011).
Obesity (1 paper, 2020). Accumulation of substantial excess body fat. "Finally, we also investigated the Reverse Phase Protein Arrays (RPPA) data and confirmed several reported tumor regulating proteins were differentially expressed in obesity group, including 14-3-3β, GTP-binding protein Di-Ras3 (ARHI), Fatty Acid Synthase (FASN) and ribosomal protein S6 (RPS6)." (PMID 33197880, 2020).
pleural mesothelioma (1 paper, 2016). A neoplasm that arises from the mesothelial cells of the pleura. "Multiple studies reported RPS6 as a predictive marker in pleural mesotheliomas with platinum-based chemotherapy, but these findings may be coincidental." (PMID 26918730, 2016).
poliovirus infection (1 paper, 2025). An disease or disorder caused by infection with Enterovirus C. "The phosphorylation of RPS6 and translation of RP mRNA can inhibit host protein synthesis caused by poliovirus infection." (PMID 40530025, 2025).
primary central nervous system lymphoma (1 paper, 2021). A non-Hodgkin or Hodgkin lymphoma that arises in the brain or spinal cord as a primary lesion. "More interestingly, mTOR-independent phosphorylation of RPS6 was frequently identified in primary central nervous system lymphoma (PCNSL) and DLBCL." (PMID 35008473, 2021).
retinoblastoma (1 paper, 2014). A malignant tumor that originates in the nuclear layer of the retina. "Indeed, in our study metformin activated the AMPK pathway in retinoblastoma cell lines at mM levels, as indicated by ACC phosphorylation and decreased phosphorylation of ribosomal protein S6 (a downstream effector of mTOR) and 4E-BP1 (a downstream effector of S6K)." (PMID 25215935, 2014).
skin inflammation (1 paper, 2023). "AD-like skin inflammation was induced by a 7-day treatment of MC903 (calcipotriol), and ribosomal protein S6 was highly phosphorylated in inflamed tissues." (PMID 36983043, 2023).
thymoma (1 paper, 2013). A neoplasm arising from the epithelial cells of the thymus. "In B3 thymomas, most of the enriched pathways concerned translation, including down-regulation of the ribosomal protein genes RPS6 and RPS18, which is rare in other cancers." (PMID 24427739, 2013). "Since RPS6 is an effector of the AKT/mTOR pathway, we studied expression of its negative regulators PTEN and PIK3R1 but found them up-regulated only slightly (p < 10−3) in B3 thymomas." (PMID 24427739, 2013).
type 2 diabetic (1 paper, 2024). "On the other hand, RPS6 was reported to cause metabolic abnormalities in type 2 diabetic patients and may also play a role in reducing focal adhesion through the PI3K-Akt-mTOR signaling pathway." (PMID 38331889, 2024).
tumor (113 papers, 2005 to 2026). "We report that AKT(T308) is positively associated with plasma insulin levels in LLC fast mice and rpS6 was negatively associated with tumour growth rate." (PMID 40931444, 2025). "Chronic hepatic Rps6 insufficiency also predisposed to hepatomegaly and spontaneous tumor development that was accelerated by loss of the tumor suppressor Pten." (PMID 36656901, 2023). "The hepatomegaly and spontaneous tumor development in ΔS6 livers prompted us to further explore the idea that hepatic Rps6 deficiency was a priming event for tumor development." (PMID 36656901, 2023). "An earlier study suggested that RPS6 phosphorylation is associated with early events of OSCC tumor progression." (PMID 35008473, 2021). "S1 cells exhibited lower cellular ATP levels and reduced p70S6K/p-rpS6 signals, which were the possible causes of smaller tumor mass in the nude mice." (PMID 29467934, 2018). "Inhibition of these pathways in vivo in an LL/2 tumor mouse model increased survival, inhibited tumor growth, and decreased angiogenesis associated with decreased RPS6 and SMAD2 phosphorylation." (PMID 27618721, 2016). "This reparative reaction is characterized by tumor neovascularization accompanied by infiltration of immune cells and carcinoma-associated fibroblasts that stain for phosphorylated ribosomal protein S6 (pS6), downstream the PI3K/Akt/mTOR pathway." (PMID 26098779, 2015). "Fluorescence in situ hybridisation analysis for mTOR and RPS6 loci showed that 11 of 33 and 21 of 44 tumours had loss of one copy of the respective genes, results which correlated with the loss of the relevant total proteins." (PMID 19401700, 2009). "Particularly, highly phosphorylated RPS6KB1 (p-RPS6) and RPS6 (p-RPS6) were linked to noticeably lower overall survival rates, suggesting that mTOR pathway activation might be involved in tumor aggressiveness." (PMID 40002868, 2025). "In addition, p-RPS6 deficiency reduced the development of the MyrAKT1-induced hyperplasia and tumor formation in β cells (insulinoma)." (PMID 35008473, 2021). "In contrast, rpS6 phosphorylation deficiency efficiently restrained the reduction in nuclear localization of the cell cycle inhibitor p27, as well as the development of Akttg-driven hyperplasia and tumor formation in β-cells." (PMID 26919188, 2016). "However, the role of translation infidelity in tumor suppression cannot simply be inferred from this heterologous experimental model, as rpS6 phosphorylation deficiency unexpectedly elevated the resistance of Akttg fibroblasts to proteotoxic, genotoxic as well as autophagic stresses." (PMID 26919188, 2016). "Such regions revealed high expression of SOX2 and RPS6, both of which play critical roles in promoting tumour progression." (PMID 40940922, 2025). "JNK and yorkie (yki) mediate their upregulation through the activation of the nutrient sensor mTOR and phosphorylation of ribosomal protein S6 (RpS6) to promote tumour growth and invasion." (PMID 39682725, 2024). "It has been previously established that p70S6K/RPS6 is a pivotal regulator of tumor cell metabolism." (PMID 39325536, 2024). "We observed that the inhibition of p70S6K/RPS6 using everolimus or the use of 4EBP1A4, the unphosphorylatable form of 4EBP1, blocked tumor development in these mice." (PMID 39325536, 2024). "Comparison of genes differentially expressed between the subcluster C9 of exhausted CD8+ cells from tumors and normal tissues showed GNLY and ITM2A were highly expressed in normal tissues, and high expression of FABP5 and RPS6 was exhibited in tumor tissues." (PMID 35874785, 2022). "For example, it has been reported that RPS6 is activated by tumor microenvironment conditions and hypoxia in endothelial cells." (PMID 35008473, 2021).
tumor (continued). "Immunohistochemistry analysis of phospho rpS6 in the tumour region shows a reduction consistent with mTOR inhibition." (PMID 34389715, 2021). "RPS6-KD suppressed the tumor-sphere formation of GBM cells through the inhibition of p-JAK2 and p-STAT3 and concomitantly downregulated the stemness-related proteins Nestin and SOX2." (PMID 35008473, 2021). "Inversely, RPS6 overexpression facilitated the tumor sphere formation, and the STAT3 inhibitor, AG490, antagonized the RPS6-enhanced sphere formation." (PMID 35008473, 2021). "Targeting RPS6 by siRNA or drug inhibitors induces tumor regression in resistant cells and models both in vitro and in vivo." (PMID 34873618, 2021). "The TMAs were probed with antibodies against Ki67 to assess tumour cell proliferation and selected proteins identified as upregulated in the primary MpM-derived cell lines, including eIF4A, rpS6, ATP5A and SDH." (PMID 34389715, 2021). "Torin1 alone or in combination significantly decreased downstream mTOR activity, as measured by the ratio of phosphorylation of rpS6 relative to total rpS6 within the tumor samples." (PMID 34031411, 2021). "The addition of glexatinib or crizotinib to erlotinib synergistically reduced tumor growth in a patient-derived xenograft (PDX) model with consistent reduction in p-ERK1/2 and p-RPS6 in PDX tumor samples." (PMID 34207383, 2021). "IHC analysis and western blot analyses revealed that the levels of p-mTOR, p-p70S6K, and p-RPS6 in tumor tissues were inhibited by DHA in vivo." (PMID 33658929, 2020). "RPS6 is an indispensable ribosomal RNA-binding protein, which has a vital role in tumor transformation and cell cycle arrest, as well as cell proliferation, migration, and invasion." (PMID 32862831, 2020). "Growing evidence suggests that RPS6KB1 and RPS6, two key proteins in the mTOR pathway, as crucial drivers of tumor onset, progression and BRAFi resistance." (PMID 33082316, 2020). "In parallel, exercise mitigates tumor progression through a decrease in phosphorylated ribosomal protein S6." (PMID 32486073, 2020). "In the present study, the expression of p-mTOR, together with its activators (i.e., p-Akt, p-AMPK) and downstream effectors (i.e., p-p70S6K and p-RPS6) was more intense in the tumour edge." (PMID 30650598, 2019). "Highly p-rpS6 expressing tumor samples showed stable disease after two cycles of therapy, low expressing tumors showed progressive disease." (PMID 26506236, 2016). "In contrast to pERK, immunostaining to detect phosphorylated ribosomal protein S6 (pS6), an indicator of mTOR signaling, was detected broadly throughout the tumor masses." (PMID 26859571, 2016). "The present report expands the reliance on rpS6 phosphorylation to tumor development in the endocrine pancreas." (PMID 26919188, 2016). "One important result of our study is the crucial functional relevance of rpS6 in mediating the anti-tumor effects of Everolimus." (PMID 26506236, 2016). "Of the 316 tumor specimens, 262 cases (82.91 %) were positively stained with t-rpS6 and 165 patients (52.22 %) revealed the p-rpS6 positive expression." (PMID 26490682, 2015). "While the staining for phospho-RPS6 (Ser235/236) and phospho-RPS6 (Ser240/244) was mostly restricted to the cytoplasm of cells we detected phospho-4EBP1 (Thr37/46) also in tumor cell nuclei." (PMID 25993328, 2015). "The phosphorylation of ribosomal protein S6 (p-S6) is widely used as an indicator of mTOR activity in human tumor specimens." (PMID 25057912, 2014). "Combined treatment with crizotinib and an ATP-competitive mTOR inhibitor abrogated RPS6 phosphorylation, leading to reduced tumor growth and prolonged survival in ALKF1174L/MYCN-positive models compared to single agent treatment." (PMID 25228590, 2014). "The tumor tissue remaining after treatment with rapamycin demonstrated increased pERK1/2 or persistent phosphorylated ribosomal protein S6 (pS6), indicating potential resistance mechanisms." (PMID 23593290, 2013).